CHAC2 (ChaC glutathione specific gamma-glutamylcyclotransferase 2)
Diseases named in the same sentence as CHAC2 in open-access papers (continued):
Sharing a sentence is not in itself a finding about the gene and the disease.
lung adenocarcinoma (1 paper, 2023). A carcinoma that arises from the lung and is characterized by the presence of malignant glandular epithelial cells. "We performed a series of gain-of-function and loss-of-function assays, and these studies found that CHAC2 promoted the proliferation of lung adenocarcinoma cells in vitro and in vivo, whereas knockout of CHAC2 significantly attenuated the proliferation of lung adenocarcinoma cells." (PMID 37283797, 2023). "Immunohistochemical assays showed that the protein value of CHAC2 was also obviously elevated in lung adenocarcinoma compared with normal lung tissues." (PMID 37283797, 2023). "The results showed that CHAC2 exhibited higher expression in lung adenocarcinoma than in normal lung tissue." (PMID 37283797, 2023). "Subsequent immunoblot, immunohistochemistry and flow cytometry experiments showed that CHAC2 increased ROS by reducing GSH in lung adenocarcinoma and that the elevated ROS activated the MAPK pathway." (PMID 37283797, 2023). "Here, we found that CHAC2 promoted the proliferation of lung adenocarcinoma cells, and overexpression of CHAC2 reduced the intracellular quantity of GSH and elevated the intracellular quantity of ROS." (PMID 37283797, 2023). "To further examine the influence of CHAC2 on the progression of lung adenocarcinoma, we explored the expression profile of CHAC2 using public databases." (PMID 37283797, 2023). "In this study, TCGA analysis showed that the mRNA levels of CHAC2 were significantly higher in lung adenocarcinoma samples than in normal lung samples." (PMID 37283797, 2023). "Here, RNA sequencing data analysis and immunohistochemistry (IHC) assays of lung adenocarcinoma and normal lung tissues were used to verify the expression of CHAC2." (PMID 37283797, 2023). "We found that CHAC2 activated the MAPK pathway by regulating ROS levels in lung adenocarcinoma cells and therefore promoted lung adenocarcinoma." (PMID 37283797, 2023). "Altogether, we observed that CHAC2 is significantly elevated in lung adenocarcinoma and contributes to the development of lung adenocarcinoma." (PMID 37283797, 2023). "Bioinformatics analysis revealed that CHAC2 regulated the cell cycle and apoptotic pathways in lung adenocarcinoma cells, and these regulatory effects were validated by flow cytometry assays." (PMID 37283797, 2023). "Our investigation identified a new role for CHAC2 and elucidated the mechanism by which CHAC2 promotes lung adenocarcinoma progression." (PMID 37283797, 2023). "The effect of CHAC2 on the proliferation abilities of lung adenocarcinoma cells was examined using a series of overexpression or knockout assays." (PMID 37283797, 2023). "In summary, this study affords new insights into the expression, function and regulatory pathways of CHAC2 in lung adenocarcinoma." (PMID 37283797, 2023). "Subsequent experiments further demonstrated that CHAC2 promoted the growth capacity of lung adenocarcinoma by elevating the level of ROS and activating the MAPK signaling pathway." (PMID 37283797, 2023). "RNA sequencing and IHC results showed that the expression level of CHAC2 in lung adenocarcinoma was higher than that in normal lung tissues." (PMID 37283797, 2023). "In this study, we explored the expression profile of CHAC2 in lung adenocarcinoma using public databases, followed by RNA sequencing and immunohistochemistry using clinical tissue samples." (PMID 37283797, 2023). "Overexpression of CHAC2 activates the MAPK signaling pathway in lung adenocarcinoma." (PMID 37283797, 2023). "Finally, sequencing analysis showed that CHAC2 activated the MAPK pathway in lung adenocarcinoma cells, and rescue experiments showed that CHAC2 activated the MAPK pathway by increasing the level of ROS." (PMID 37283797, 2023). "Western blot and IHC experiments confirmed that CHAC2 was highly expressed in lung adenocarcinoma." (PMID 37283797, 2023).
lung adenocarcinoma (continued). "However, it is not clear whether other enzymes, especially the newly identified CHAC2, regulate the level of ROS and growth capacity of lung adenocarcinoma." (PMID 37283797, 2023). "In this study, we found that elevated CHAC2 decreased the levels of GSH and increased the intracellular levels of ROS, thereby activating the MAPK signaling pathway in lung adenocarcinoma cells." (PMID 37283797, 2023). "In this study, we found that CHAC2, a GSH metabolic enzyme, was highly expressed in lung adenocarcinoma and promoted the progression of lung adenocarcinoma." (PMID 37283797, 2023). "Combined with the molecular background of CHAC2, we found that CHAC2 reduced GSH levels and increased ROS levels in lung adenocarcinoma cells." (PMID 37283797, 2023). "The role of CHAC2, an enzyme regulating GSH, in lung adenocarcinoma remains unknown." (PMID 37283797, 2023).
lymphoma (1 paper, 2024). A malignant (clonal) proliferation of B- lymphocytes or T- lymphocytes which involves the lymph nodes, bone marrow and/or extranodal sites. "CHAC2 was commonly reduced upon LSD1 inhibition in LMP1-expressing lymphoma cells, but not in control cells." (PMID 38514636, 2024).
teratoma (1 paper, 2019). A non-seminomatous germ cell tumor characterized by the presence of various tissues which correspond to the different germinal layers (endoderm, mesoderm, and ectoderm). "On the contrary, the downregulation of ChaC2 resulted in the decrease of cell proliferation and the induction of cell death in human embryonic stem cells, and ChaC2 knockdown decreased the teratoma size and enriched teratoma adipocytes." (PMID 31878259, 2019).
tumor (11 papers, 2017 to 2025). "Additionally, we analyzed the promoter methylation levels of CHAC2 as changes in the methylation status of various oncogenes and tumor suppressors are linked with cancer progression." (PMID 36568153, 2022). "Current research on CHAC2 predominantly focuses on tumor biology, with limited exploration of its involvement in bone-related studies." (PMID 39854306, 2025). "Primarily, CHAC2 can inhibit tumor progression by decreasing cellular GSH levels and inducing mitochondrial apoptosis." (PMID 41488051, 2025). "In disease contexts, CHAC2 is often found at reduced levels in some cancers, such as gastric and colorectal cancers, where it acts as a tumor suppressor by promoting apoptosis and autophagy through ER stress pathways." (PMID 39534397, 2024). "We further looked into the CHAC2 expression patterns using the bcGenexminer database within the adjacent tumor area and the transcript levels of CHAC2 were high in tumor samples compared to adjacent normal and healthy controls." (PMID 36568153, 2022). "In the present study, we have investigated the transcriptomic data of CHAC2 expression in breast normal-like vs. tumor samples and molecular subtypes." (PMID 36568153, 2022). "We found that CHAC2 mRNA expression enhanced with increasing tumor grading according to NPI and SBR grading." (PMID 36568153, 2022). "From the pan-cancer analysis it is clear that CHAC2 has a different expression in different tumor tissue and therefore, mechanistic studies are warranted to conclude the factors behind the differential expression." (PMID 36568153, 2022). "CHAC2 was expressed at high levels in tumor tissues compared to adjacent normal tissues as per UALCAN and the GEPIA2 database." (PMID 36568153, 2022). "And CHAC2 acted as a tumor suppressor inducing mitochondrial apoptosis and autophagy simultaneously through UPR." (PMID 28837156, 2017). "Our results showed for the first time that CHAC2 was degraded by the ubiquitin-proteasome pathway and CHAC2 expression inhibited tumor cell growth, proliferation, migration in vitro and in vivo." (PMID 28837156, 2017). "At last, we evaluated the effects of CHAC2 on tumor cell growth in vivo by injection of SW620-CHAC2 and SW620-vector into BALB/c nude mice cells (n=6, respectively)." (PMID 28837156, 2017). "However, CHAC2 expression is essential to inhibiting tumor growth, proliferation, and migration, as CHAC2 induces mitochondrial apoptosis and autophagy." (PMID 39199310, 2024). "Moreover, the analysis according to the prognostic index like Nottingham prognostic index (NPI) and Scarff Bloom and Richardson (SBR) grade status revealed a direct correlation of CHAC2 expression with increasing tumor grade and stage." (PMID 36568153, 2022). "Immunohistochemistry and western blot revealed that CHAC2 was downregulated in most tumor tissues, and 3-year survival rate of patients with high CHAC2 expression was significantly higher than that of patients with low CHAC2 expression (P<0.001 and P=0.001, respectively)." (PMID 28837156, 2017). "However, in certain cancers like breast cancer, CHAC2 expression may be elevated, contributing to tumor progression by increasing oxidative stress and activating pathways such as MAPK signaling." (PMID 39534397, 2024). "The percentage of spontaneous and 5-FU-induced apoptotic cells was significantly lower in CHAC2 knockdown cells as compared with the negative control cells, which further confirmed that CHAC2 induced tumor cell apoptosis." (PMID 28837156, 2017).
cancer (8 papers, 2017 to 2025). A tumor composed of atypical neoplastic, often pleomorphic cells that invade other tissues. "While several studies have reported a dual role for CHAC1 in cancer progression, studies depicting the association of CHAC2 in carcinogenesis are sparse." (PMID 36568153, 2022). "In this context, CHAC2 expression promotes cancer growth, inhibits apoptosis and accelerates cell cycle progression through MAPK hyperactivation." (PMID 41488051, 2025). "In contrast to CHAC1, the general role of CHAC2 in cancer and programmed cell death remains elusive." (PMID 41488051, 2025). "This suggests that CHAC2 plays a dual role, maintaining cellular balance in normal conditions while influencing cancer development in a context-specific manner." (PMID 39534397, 2024). "Several studies have found the function of degrading GSH as CHAC1 in cancer; however, the role of CHAC2 in GSH degradation remains controversial in different cancers." (PMID 36899832, 2023). "Subsequently, a pan-cancer analysis of CHAC2 expression in various cancers and we attempted the same by utilizing UALCAN, TNMplot, GENT2, and TIMER2 database to perform the analysis." (PMID 36568153, 2022). "Collectively, our researches shed light on the molecular basis of a glutathione-controlling ChaC2 enzyme and suggest its role in cancer cell proliferation." (PMID 31878259, 2019). "Thus, like CHAC1, CHAC2 represents an intriguing and complex target for further cancer research." (PMID 41488051, 2025). "Current evidence indicates that CHAC2 helps maintain GSH homeostasis and may also play a role in cancer progression and development." (PMID 41488051, 2025). "Our structural and functional analyses of ChaC2 will contribute to the development of inhibitors for the ChaC family, which could effectively regulate the progression of GSH degradation-related cancers." (PMID 31878259, 2019). "Overexpression of ChaC2 mutants at the active site would result in the increase of the intracellular GSH level and the inhibition of Nrf2, which would elicit anti-proliferative effects on cancer cells." (PMID 31878259, 2019).
CHAC2 also shares sentences with these, for which no sentence is quoted: Hepatitis (1 paper); Legg-Calve-Perthes disease (1); lymph node metastasis (1); sarcoma (1).